DNMT3B (DNA methyltransferase 3 beta)
Diseases named in the same sentence as DNMT3B in open-access papers (continued):
Sharing a sentence is not in itself a finding about the gene and the disease.
lung carcinoma (continued). "For example, it would have been desirable to have genotyped nsSNPs mapping to DNMT1 and DNMT3b, given previously published data implicating variation in these genes in development and prognosis of lung cancer." (PMID 17533396, 2007). "In addition, both DNMT3A and DNMT3B extend the epigenetic remodeling of lung cancer cells beyond the classical hypermethylation of promoter CpG islands." (PMID 41303477, 2025). "Interestingly, DNMT3B shows increased expression while miRNA 29b mRNA expression is low in the whole blood of patients with lung cancer compared to healthy controls." (PMID 40003580, 2025). "The authors concluded that cigarette smokers with increased DNMT3b and low miRNA 29b expression are at a higher risk of developing lung cancer than non-smokers with lower DNMT3B and higher microRNA-29b." (PMID 40003580, 2025). "Moreover, FOXO3 represses the DNA methyltransferase 3B (DNMT3B) by interacting with a binding site within the DNMT3B promotor in human lung cancer cell lines (A549 and CL1-5) in vitro." (PMID 38132107, 2023). "miR-148b directly controls DNMT1 and DNMT3b in lung cancer cells." (PMID 36959680, 2023). "Even among non-smokers, those with lower miR-29b expression and higher DNMT3B mRNA expression also had a higher risk of developing lung cancer (OR 3.18, 95% CI 1.65–6.15)." (PMID 35627221, 2022). "It seems that subjects who have lower miR-29b and/or higher DNMT3B mRNA expression are likely to reveal lung cancer risk regardless of cigarette exposure." (PMID 35627221, 2022). "Our results suggested that smokers and green tea nondrinkers with lower miR-29b expression and higher DNMT3B mRNA expression are more susceptible to lung cancer development." (PMID 35627221, 2022). "However, studies have previously reported that DNMT3B was an oncogene that played a crucial role in the progression of various types of cancer, including endometrial cancer (EC), lung cancer, and PCa, and conversely DNMT3B has implicated as a TSG in lymphoma." (PMID 36091786, 2022). "In addition, this study evaluated the combined effects of cigarette smoking and green tea consumption with miR-29b and DNMT3B mRNA expression in the development of lung cancer." (PMID 35627221, 2022). "Notably, a significant interaction between green tea consumption and DNMT3B mRNA expression was also observed in lung cancer development." (PMID 35627221, 2022). "In the present study, green tea consumption was observed to be associated with DNMT3B mRNA expression, but not miR-29b expression, especially in lung cancer patients with higher DNMT3B mRNA expression." (PMID 35627221, 2022). "Therefore, smokers with lower miR-29b expression or higher DNMT3B mRNA expression are more likely to develop lung cancer." (PMID 35627221, 2022). "However, the sample size in the current study was too small to detect the interaction effect of miR-29b and DNMT3B mRNA expressions in lung cancer development." (PMID 35627221, 2022). "Future studies require further investigation of whether miR-29b and DNMT3B mRNA expression are inversely affected by lung cancer progression." (PMID 35627221, 2022). "Our study suggests that smokers and green tea nondrinkers with lower miR-29b expression and higher DNMT3B mRNA expression are more susceptible to lung cancer development." (PMID 35627221, 2022). "Compared to non-smokers with both higher miR-29b and lower DNMT3B mRNA expression, smokers with both low miR-29b and higher DNMT3B mRNA expression had an elevated risk of lung cancer development (OR 5.12, 95% CI 2.64–9.91)." (PMID 35627221, 2022). "Interactions of smoking with miR-29b or DNMT3B mRNA expression in lung cancer were significant." (PMID 35627221, 2022).
lung carcinoma (continued). "However, the respective relationships between nearly all analyzed variables and miR-29b expression and DNMT3B mRNA expression in lung cancer patients showed a different direction compared with the results in healthy controls." (PMID 35627221, 2022). "Moreover, more lung cancer cases than controls were DNMT3B − 149 TT genotype carriers (96.3% vs 90.8%, OR: 1.62, 95% CI: 1.35–1.94)." (PMID 34587932, 2021). "For example, the expression level of miR-29s was found to be inversely correlated with DNA methyltransferase 3A (DNMT3A) and DNA methyltransferase 3B (DNMT3B) in lung cancer tissues by controlling methylation to inhibit the reexpression of tumor suppressor genes and inhibit tumorigenesis." (PMID 34789236, 2021). "A study conducted in a non-Hispanic Caucasian population also showed that DNMT3B − 149 T allele was associated with increased lung cancer risk." (PMID 34587932, 2021). "Compared to nonsmokers carrying the DNMT3B − 149 CT genotype, smokers carrying the TT genotype had a greater lung cancer risk (odds ratio [OR]: 2.83, 95% confidence interval [CI]: 1.62–4.93)." (PMID 34587932, 2021). "DNMT3B complex showed up-regulation in lung cancer for sEVs and tumor tissue." (PMID 33233545, 2020). "For DNMT3B −2437T>A polymorphism, when TT genotype was used as reference, the A-allele carrier genotypes (AT+AA) were not remarkably related to lung cancer risk (OR = 0.99, 95% CI, 0.74 to 1.33, P = 0.168)." (PMID 27876061, 2016). "The two DNMT3B polymorphisms are not correlated with lung cancer risk among Chinese population nor the haplotype of them." (PMID 27876061, 2016). "Increased DNMT3B expression has been discovered in lung cancer." (PMID 27876061, 2016). "In our study, the final fall in expression of de novo Dnmt3a and Dnmt3b could be explained by the recent demonstration of downregulation after induction of EMT by TGFβ in lung cancer cells." (PMID 27129173, 2016). "These collectively suggest that DNMT3B’s role in lung cancer development might require involvement of other genes’ regulations." (PMID 27876061, 2016). "In conclusion, two DNMT3B polymorphisms, −149C>T and −2437T>A, are not related to lung cancer risk among Chinese population nor the haplotype of them." (PMID 27876061, 2016). "The miR-29 family reverts aberrant methylation in lung cancer by targeting DNMT3a and DNMT3b." (PMID 24987964, 2014). "In addition to a previous study that reported that the miR-29 family regulated both DNMT3A and DNMT3B in lung cancer, in this study we showed that DNMT3A is regulated by miR-143 in CRC." (PMID 19638978, 2009). "While another study showed that Dnmt3b knockdown could arrest lung cancer cell growth, assist apoptosis and re-activate the TSG, which has been silenced due to hypermethylation." (PMID 20119531, 2009). "It is also commonly acknowledged that DNMT3B correlated with TSG hypermethylation in lung cancer." (PMID 20119531, 2009). "Interestingly it was shown that hsa-mir-29c directly targets DNA-methyl transferase 3A (DNMT3A) and 3B (DNMT3B) in lung cancer tissue." (PMID 18493317, 2008). "Therefore, targeted inhibition of the FOXO3a/DNMT3B/MDM2 axis might be seen as a new therapeutic direction for lung cancer treatment, making the existence of the epigenetic linkage with this pathology evident." (PMID 39165584, 2024). "However, downregulation of FOXO3 promoted DNMT3B overexpression, leading to tumor growth in lung cancer, while clinical findings also showed that there was a high DNMT3B, low FOXO3a, and high MDM2 expression associated with low survival rates in lung cancer patients." (PMID 35847844, 2022). "When miR-29b was replaced by DNMT3B, smokers with higher DNMT3B mRNA expression (OR 2.96, 95% CI 1.94–4.50) and smokers with lower DNMT3B mRNA expression (OR 1.17, 95% CI 0.72–1.89) also had an increased risk of lung cancer compared to non-smokers with lower DNMT3B mRNA expression." (PMID 35627221, 2022).
lung carcinoma (continued). "Green tea nondrinkers with both lower miR-29b and higher DNMT3B mRNA expression levels had a 3.23-fold (95% CI 1.55–6.72) increased risk of lung cancer, and this interaction of green tea consumption with miR-29b and DNMT3B mRNA expression was significant in lung cancer development (p < 0.001)." (PMID 35627221, 2022). "However, the effect of green tea intake on the simultaneous expression of miR-29b and DNMT3B mRNA, which may be engaged in the development of lung cancer, is still unclear." (PMID 35627221, 2022). "Our findings indicated that DNMT3B −149C>T polymorphism might not be used as the prognostic marker for lung cancer, especially in Chinese population." (PMID 27876061, 2016). "A previous case-control study has demonstrated the hypothesis that T allele in DNMT3B −149C>T polymorphism is tightly related to the increased risk of lung cancer among non-Hispanic whites." (PMID 27876061, 2016). "In conclusion, these findings provide a rationale for targeting DNMT3B-mediated HOPX DNA methylation and identify crucial molecular targets for lung cancer therapy." (PMID 41660264, 2025). "Furthermore, abnormal activation of DNMT3A and DNMT3B is closely related to the early occurrence of lung cancer, and their inhibitors (such as azacitidine and decitabine) have been approved for use in hematological tumors and are being explored for epigenetic therapy in lung cancer." (PMID 41394878, 2025). "This successful up-regulation of the DNMT3B gene, out of the complex relationship with both FOXO3a and MDM2, results in poor prognosis for lung cancer patients." (PMID 39165584, 2024). "The protein DNA (cytosine-5)-methyltransferase 3β (DNMT3B) complex, as well, was significantly upregulated in BAL EV from lung cancer patients." (PMID 36829523, 2023). "Gallic acid (GA) alters methylation of lung cancer and pre-malignant oral cell lines, and significantly suppresses cytoplasmic and nuclear DNMT1 and DNMT3B within 1 week." (PMID 36232871, 2022). "DNMT3B has been reported to be overexpressed in breast, oral, and colorectal tumor tissues, while other studies have suggested that DNMT3B and DNMT3A are tumor suppressor genes for lymphoma and lung cancer." (PMID 31024853, 2019). "We show that gallic acid (GA) changes the methylome of lung cancer and pre-malignant oral cell lines and markedly reduces both nuclear and cytoplasmic DNMT1 and DNMT3B within 1 week." (PMID 29416619, 2018). "Protein levels of DNMT1, DNMT3b, and HDAC in the HPV16-positive or HPV16 E6-transfected lung cancer cells were higher than in the HPV-negative or HPV16 E6 knockdown cells." (PMID 26918347, 2016). "To analyze the gene expression of different DNMTs, we noticed an increasing trend in DNMT‐1, DNMT‐3A, and DNMT‐3B gene expression in hypoxic lung cancer cells compared to normoxia." (PMID 35658112, 2024). "The miRNA-29 family, on the other hand, may restore aberrant methylation in lung cancer by targeting the 3'-untranslated region of DNMT3A and DNMT3B, which are typically overexpressed in lung cancer and are associated with a poor prognosis." (PMID 34820248, 2021). "MiR-29 family reverts abnormal methylation in lung cancer by targeting DNA methyltransferases 3A and 3B (DNMT3A and DNMT3B), induces re-expression of methylation-silenced tumor suppressor genes, such as FHIT and WWOX, and inhibits tumorigenicity in vitro and in vivo." (PMID 34299277, 2021). "Increased expression of DNMT3B was reported in non-smoking female lung cancer patients with HPV16 or HPV18 positive tumors, but the role of E6 and E7 was not investigated." (PMID 34361112, 2021). "A previous study revealed that the reversion of the miR-29 family on abnormal methylation in lung cancer is mediated though regulation of DNMT3A and DNMT3B, two critical de novo DNA methyltransferases that are frequently upregulated in patients with idiopathic pulmonary fibrosis." (PMID 30906331, 2019).
lung carcinoma (continued). "Moreover, in case of lung cancer and leukaemia this interaction of miR29b with DNMT3A, DNMT3B and SP1 has already been proved." (PMID 30496316, 2018). "Only few direct transcriptional regulators of DNMT3B such as SP1, SP3 or FOXO3A have been identified and only few that are known have such a clear and important link to cancer (for example, FOXO3A negatively regulates DNMT3B promoter activity in lung cancer)." (PMID 29100357, 2017). "However, the effect of simultaneous miR-29b and DNMT3B mRNA expression in the development of lung cancer has not been explored." (PMID 35627221, 2022). "However, studies have not explored the effect of simultaneous miR-29b and DNMT3B mRNA expression in the development of lung cancer." (PMID 35627221, 2022). "However, researchers have not yet elucidated the effect of DNMT3B mRNA expression in the development of lung cancer." (PMID 35627221, 2022). "Although SV40 LT can upregulate the expression of DNMT3B, thereby contributing to the oncogenic phenotype in a lung cancer model, it is not recognized whether MCPyV LT can affect the expression levels or activity of specific DNMTs." (PMID 34361112, 2021). "While in the presence of miR-101, the expression of DNMT1 and DNMT3B did not change significantly, indicating that DNMT3A is a direct target of the miR-101 in lung cancer cells." (PMID 32751889, 2020).
ICF syndrome (63 papers, 2004 to 2026). "DNMT3B mutations are associated with immunodeficiency, centromeric instability, and facial anomalies (ICF) syndrome." (PMID 39996888, 2025). "Approximately half of patients with ICF syndrome have DNMT3B mutations, while the other half have mutations in genes indirectly affecting DNMT3B-mediated methylation, such as LSH." (PMID 39996888, 2025). "Mutations in DNMT3B are linked to immunodeficiency, centromeric instability, and facial anomalies (ICF) syndrome." (PMID 39996888, 2025). "Although ICF syndrome‐related missense mutations in the DNMT3B have been identified, their precise impact on protein structure and function remains inadequately explored." (PMID 39290110, 2024). "Here, we delve into the impact of four ICF syndrome‐linked mutations situated in the DNMT3B dimeric interface (H814R, D817G, V818M, and R823G), revealing that each of these mutations compromises DNA‐binding and methyltransferase activities to varying degrees." (PMID 39290110, 2024). "Nevertheless, a three-amino-acid insertion immediately downstream of the DNMT3C E693-corresponding site in DNMT3B has been shown to be associated with the ICF syndrome and perturb protein localization in cells." (PMID 39098534, 2024). "Mutations in DNMT3B are associated with human genetic diseases, particularly immunodeficiency, centromere instability, facial anomalies (ICF) syndrome." (PMID 39290110, 2024). "DNMT3B is the only gene among those involved in the ICF syndrome pathogenesis that is clearly associated with DNA methylation homeostasis." (PMID 39040103, 2024). "Approximately 60% of ICF syndrome patients carry a mutation in DNMT3B, classified as Type 1 ICF (ICF1), leading to DNA hypomethylation in classical satellites 2 and 3 at centromeric regions of chromosomes 1, 9, and 16, resulting in centromeric instability." (PMID 39290110, 2024). "Recent studies have shown that the structure of DNMT3b’s methyltransferase domain is more susceptible to mutations associated with ICF syndrome compared to its complex with DNMT3L." (PMID 39376563, 2024). "Mutations in HELLS, its activator CDCA7, and the de novo DNA methyltransferase DNMT3B, cause immunodeficiency-centromeric instability-facial anomalies (ICF) syndrome, a genetic disorder associated with the loss of DNA methylation." (PMID 37769127, 2023). "Previous studies have linked ICF syndrome to homozygous or compound heterozygous mutations of DNMT3B, occurring in approximately half of the patients with ICF syndrome." (PMID 35869095, 2022). "Mutations of DNMT3B are associated with human diseases, notably the immunodeficiency, centromeric instability and facial anomalies (ICF) syndrome." (PMID 35869095, 2022). "Dnmt3bCI/CI also had craniofacial defects including shortened nose, which is typical of ICF syndrome observed in humans and linked to DNMT3B mutations." (PMID 33450231, 2021). "ICF1 is caused by mutations in DNMT3B, which encodes the DNA methyltransferase 3B and is the most frequent type of ICF syndrome, accounting for more than half of patients." (PMID 33995370, 2021). "Only 2 decades later the discovery of the ICF syndrome, mutations in the DNMT3B gene were identified as the cause of the disease, making it the first genetic disease induced by DNA methyltransferase dysfunctions." (PMID 34082816, 2021). "Loss of Dnmt3b’s CA induces phenotypes consistent with ICF syndrome in humans, in particular craniofacial defects and less efficient adult hematopoiesis." (PMID 33450231, 2021). "The divergent substrate preference between DNMT3A and DNMT3B provides an explanation for site-specific epigenomic alterations seen in ICF syndrome with DNMT3B mutations." (PMID 32620778, 2020). "For example, mutations in DNMT3B occur in the majority of patients with Immunodeficiency, Centromere instability and Facial anomalies (ICF) syndrome." (PMID 33152014, 2020).